HIF1A (hypoxia inducible factor 1 subunit alpha)
Diseases named in the same sentence as HIF1A in open-access papers (continued):
Sharing a sentence is not in itself a finding about the gene and the disease.
breast cancer (continued). "Our results showed a reduction in the expression of HIF1α with atovaquone treatment under both normoxic, as well as hypoxic conditions, suggesting a significant role of atovaquone in suppressing hypoxia in breast-cancer cells." (PMID 34068008, 2021). "Having discovered that TARBP2 upregulates HIF-1α through inhibiting its proteasomal degradation, we investigated the correlation between TARBP2 and HIF-1α in patients with breast cancer." (PMID 35008634, 2021). "Taken together, this study indicates the regulatory role of TARBP2 in the ubiquitination–proteasomal degradation of HIF-1α protein in breast cancer." (PMID 35008634, 2021). "As the major mediator of the adaptability of tumor cells to hypoxia, HIF-1α is constitutively activated in a broad spectrum of solid tumors, such as gastric cancer, cervical cancer, and breast cancer." (PMID 34249682, 2021). "miRNA-20b is a potential oncogene that affects the control of VEGF expression in MCF-7 breast cancer cells by targeting HIF-1α and STAT3." (PMID 34778378, 2021). "Several studies using MDA-MB-231 human breast cancer cells or EMT6 murine mammary carcinoma cells have also demonstrated that inhibition of HIF1α or HIF2α significantly diminishes metastasis to the lung." (PMID 34556788, 2021). "Genistein is an isoflavone compound extracted from soybeans reported to exert anti-cancer effects; it decreases HIF-1α levels in breast cancer cells by binding with the factor inhibiting HIF site on HIF-1α." (PMID 33562161, 2021). "MYC (and HIF1A) has previously been found to be highly expressed in human breast cancer cells treated with Poly I:C." (PMID 34681079, 2021). "Recent evidence shows that parkin binds to HIF-1α and causes HIF-1α degradation by ubiquitination, which suppresses metastasis of breast cancer cells." (PMID 33546453, 2021). "Immunohistochemical staining showed that, compared to 14-week-old JFKWT/PyMTTG mice, the Hif-1α and Jfk protein levels were clearly up-regulated in the mammary tumors of the 16-week-old JFKWT/PyMTTG mice." (PMID 34336836, 2021). "The aim of this study was to assess the effects of CBD for the angiogenesis and stemness of breast cancer cells by decreasing the expression of hypoxia-induced factor-1α (HIF-1α) through the Src/von Hippel–Lindau tumor suppressor protein (VHL) interaction." (PMID 34830821, 2021). "For example, exosomes from tumor-associated macrophages (TAMs) can transmit HIF-1α-stabilizing long noncoding RNA (HISLA) to breast cancer cells, thus enhancing aerobic glycolysis and apoptosis resistance of breast cancer cells." (PMID 34819615, 2021). "A small inhibitor of complex I, AG311, has been shown to reduce HIF-1α stabilization by increasing oxygen tension in two breast cancer mouse models (MDA-MB-231 and MDA-MB-435)." (PMID 33637686, 2021). "Upregulated expression of HIF1α and VEGF have been observed in BRCA1/2-mutated hereditary breast cancer when compared to sporadic breast cancer." (PMID 35008272, 2021). "Using the range of concentration of CoCl2 (0, 1, and 2 μM), the expression of HIF-1α was also assessed in breast cancer cells by western blot." (PMID 34055597, 2021). "The results showed that JFK knockdown significantly dampened hypoxia or HIF-1α-induced glycolysis in breast cancer cells." (PMID 34336836, 2021). "PINK1 and Parkin have been shown to suppress HIF1α stabilization; Parkin interacts directly with HIF-1α, promoting its ubiquitination at K477 and further degradation, which in turn suppresses breast cancer metastasis." (PMID 35201480, 2021).
breast cancer (continued). "Liang and colleagues found that hypoxia activated the HIF1α/VEGFA axis in breast cancer angiogenesis by inducing miR-153 expression and decreased expression of HIF1α and VEGFA, resulting in suppression of tumor angiogenesis." (PMID 34610581, 2021). "In breast cancer, oncogenic miR-429 was able to regulate hypoxia inducible factor-1α (HIF1α) pathway by directly targeting von-Hippel Lindau (VHL) mRNA, which caused increased proliferation and migration of breast cancer cells." (PMID 35004274, 2021). "Several other pathways are also capable of being activated by the CD44v in breast cancer, for example, CD44v6 induce hypoxia-inducible factor 1α (HIF1α) so as to increase rate of glycolysis." (PMID 34925920, 2021). "To test and extend the proposed working models, we investigated how MB influences HIF-1α and NO signaling pathways and cell survival by using the high-MB breast cancer cell line MDA-MB-468 in a monolayer and tumor spheroid cell culture model." (PMID 34671319, 2021). "In breast cancer patients, expression of HIF1-α showed a 90–91-fold increased expression, whereas GLUT1, a 160–161-fold increased expression, approximately (p < 0.0001)." (PMID 33888756, 2021). "Our results show that exposure of MCF-7 cells to DMOG significantly increased the expression of UCA1, providing additional evidence that UCA1 expression in breast cancer is under the control of HIF-1α." (PMID 34054950, 2021). "We demonstrated that JFK is a hypoxia-induced oncogene, and explored the clinicopathological significance of the HIF-1α-JFK axis in breast cancer progression and intervention." (PMID 34336836, 2021). "CBD can suppress angiogenesis and stem cell-like properties of breast cancer through Src/VHL/HIF-1α signaling." (PMID 34830821, 2021). "When using a low dose (5 μM) ofberberine, the AMPK/HIF-1α signaling pathway is inhibited and the expression of P-gp decreases, thereby increasing the sensitivity of breast cancer cells to chemotherapy drugs." (PMID 34502549, 2021). "We initially focused on transcription factors with reported links to breast cancer, and found that 16 transcription factors including HIF-1α, MYC, FOXP3, and E2F1 were predicted to target the JFK locus." (PMID 34336836, 2021). "It was further shown that bisphosphonates inhibit the vascular endothelial growth factor (VEGF)-mediated angiogenesis of breast cancer cells via suppression of the IGF-1/AKT/HIF-1α/VEGF axis." (PMID 34064589, 2021). "HIF-1α signaling promotes resistance to chemotherapy in cancer cell lines and murine models via multiple mechanisms including the enrichment of breast cancer stem cells (BCSCs)." (PMID 34771673, 2021). "HIF‐1α expression is frequently increased in solid cancers, including nonsmall cell lung carcinoma (NSCLC), breast carcinoma, and colorectal carcinoma, and the prognosis of patients with HIF‐1α overexpression is very poor." (PMID 33955074, 2021). "To assess the impact of primary tumor HIF1α expression on breast tumor cell dissemination to the bone, we generated an immune-competent spontaneous murine mammary carcinoma model with mammary-specific deletion of Hif1α using the Cre-lox system." (PMID 34556788, 2021). "We observed that cell lines that were positive for Cyr61 were also positive for HIF-1α in breast cancer (MDA-MB-231, Hs578t, MDA-MB-468) and DTC cell lines (BC-M1, LC-M1), suggesting a potential regulative interaction of HIF-1α with Cyr61." (PMID 33540545, 2021). "Previous studies demonstrated that curcumin affected HIFs in tumor cell proliferation and metabolic diseases, e.g., curcumin decreased growth and survival of hepatoma, and breast carcinoma cells through degradation of HIF-1α and HIF-2α." (PMID 34229599, 2021). "UBE2O expression is amplified and relates to AMPKa2/mTOR/HIF1a in human cancers, using the existing microarray database: Liu’s BCa, breast carcinoma (GEO: GSE22820, n = 176); Stephenson’s CaP, prostate carcinoma (n = 97); Taylor’s CaP (GEO: GSE21032, n = 179)." (PMID 34451875, 2021).
breast cancer (continued). "We found that HIF‐1α and Kindlin‐2 were highly expressed in invasive breast cancer and that the expression levels of HIF‐1α and Kindlin‐2 were correlated with Emax." (PMID 32436609, 2020). "To confirm the hypoxia-induced invadopodium-formation model, we investigated the effect of HIF-1α expression that increases the invasiveness of breast-cancer cells." (PMID 32858793, 2020). "The ERK/HIF-1α signaling pathway is widely associated with EMT, which promotes invasion and metastatic dissemination of breast cancer cells." (PMID 33374849, 2020). "Together, these results suggested that BMAL1 was reduced by chronic hypoxia independently of HIF-1α in breast cancer cells." (PMID 32316196, 2020). "In breast cancer, H19 acts as a ceRNA that sequesters microRNA let-7, leading to the upregulation of the let-7 target gene HIF1A that encodes HIF1α protein." (PMID 33123488, 2020). "In breast cancer, upon lactate stimulation, TAMs synthesize and secret HIF-1α-stabilizing long noncoding RNA (HISLA) wrapped in extracellular vesicles." (PMID 32174794, 2020). "While studies have suggested a specific link between HIF-1α and hormone receptor+ breast cancers, HIF-1α/β protein expression and their transcripts are culprits in all breast cancer subtypes, particularly TNBC." (PMID 33266219, 2020). "To prove the therapeutic mechanism of SGHZF in mice with breast cancer, we further investigated the expression of HIF-1α in the tumour tissue of mice by immunohistochemistry and Western blot analyses." (PMID 33414839, 2020). "In breast cancer, HIF‐1α activates collagen hydroxylases, which are important for collagen deposition." (PMID 32436609, 2020). "We next sought to natural compounds which can inhibit breast cancer cells via HIF‐1α and STAT3 pathways." (PMID 32065498, 2020). "It has been established that HIF-1α is highly expressed in poorly differentiated breast cancer than in well differentiated breast cancer." (PMID 31952335, 2020). "Studies by Hiraga and colleagues demonstrated that increased HIF1 α expression in MDA-MB-231 breast cancer cells enhanced the colonization after intracardiac inoculation." (PMID 32232008, 2020). "In mouse and human, nuclear expression of HIF1A itself is increased within breast cancer brain metastases, and in cell mixing experiments, suppression of HIF1A preferentially suppresses proliferation in the brain." (PMID 33298946, 2020). "We measured gene expression of HIF-1α in a variety of breast cancer cell lines in comparison to the mammary epithelial cell line MCF10A." (PMID 32707933, 2020). "Altogether, these data suggest that intra‐tumoral hypoxia exerts a central role upon HIF‐1α‐dependent vascularization in metastatic breast cancers disseminated to the lungs." (PMID 32686360, 2020). "To test the correlation between miRNA-cluster expressions with HIF-1α expression within tumors in an independent data set, we also extracted data from cBioPortal, which includes data from 16 different breast cancer studies." (PMID 32707933, 2020). "HIF-1α is a known regulator of metastatic niche formation in breast cancer and the development of lung metastasis in TNBC." (PMID 33374849, 2020). "Previous studies have suggested that HIF-1α overexpression can occur in an early stage of breast cancer (before the presence of angiogenesis or invasion)." (PMID 32375802, 2020). "In the present study, inhibition of HIF‐1α‐mediated apoptosis and migratory characteristics of breast cancer cells, through inactivated of NF‐κB pathway, was also confirmed." (PMID 32562470, 2020). "HIF-1α is over expressed in several types of tumors, such as breast cancer, and conditional deletion of HIF-1α leads to a primary tumor decrease and metastasis, related with a reduction in BCSC frequency." (PMID 32850424, 2020). "An in vivo study for a breast cancer model illustrated the impact of inhibiting HIF-1α via camptothecin (imbedded in a nanoparticle, CRLX101) in combination with bevacizumab." (PMID 31952335, 2020).
breast cancer (continued). "In this present study, we examined the effect of alpinetin in three breast cancer cell lines and investigated the mechanisms by which alpinetin regulates HIF‐1α expression and induces cancer cell death." (PMID 32562470, 2020). "Recently, P4HA1 was shown to play an essential role in breast cancer tumorigenesis and distant metastases by stabilizing HIF-1α via reducing its proline hydroxylation, resulting in escape from degradation." (PMID 32166002, 2020). "Both hypoxia-induced factor-1α (HIF)-1α and Nur77 have been shown to be involved in the development of breast cancer." (PMID 33245358, 2020). "In summary, we found that HIF‐1α promotes breast cancer stiffness through the integrin/FAK pathway by interacting with Kindlin‐2." (PMID 32436609, 2020). "In breast cancer, WWTR1 (also called transcriptional co-activator with PDZ-binding motif) expression is activated by HIF-1α and is important for the maintenance of breast cancer stem cells." (PMID 33121134, 2020). "As shown in a previous study, DFO induces hypoxia and the consequent expression of hypoxia-inducible factor-1 alpha (HIF-1α) in breast cancer cells." (PMID 33302911, 2020). "Chemotherapy in breast cancer induces HIF1α-dependent glutathione biosynthesis by enhancing the expression of the cystine transporter xCT (SLC7A11) and the regulatory subunit of glutamate-cysteine ligase (GCLM)." (PMID 32914752, 2020). "A tissue double immunofluorescence assay found that HIF‐1α and Kindlin‐2 were overexpressed in breast cancer and that they were mainly localized in the nucleus and cytoplasm." (PMID 32436609, 2020). "Cell mixing experiments, involving co-injection of HIF1A knockdown and control cells, demonstrated a striking reduction in brain proliferation by shHIF1A cells, with minimal effect on mammary tumor growth." (PMID 33298946, 2020). "Immunohistochemical analysis of both Brx-82 and Brx-142 CTC-derived tumors growing in the brain and the mammary gland reveals increased nuclear HIF1A staining within brain tumors versus mammary tumors (average brain: 46% HIF1A+; average mammary: 4.0% HIF1A+)." (PMID 33298946, 2020). "Wu and colleagues found that ectopic expression of miR-497 in breast cancer cells reduced HIF-1α and VEGF protein levels, thereby suppressing angiogenesis." (PMID 35006436, 2020). "This enhancement of HIF-1α protein expression further confirms that CoCl2 treatment induces hypoxia in breast cancer." (PMID 32707933, 2020). "In contrast, in the majority of mammary tumor samples, the fraction of shHIF1A cells was unchanged from input, suggesting that HIF1A has minimal effect on the growth of orthotopic mammary tumors in this model." (PMID 33298946, 2020). "Recent evidence shows that HIF-1α signalling in osteoblasts increases breast cancer metastasis towards all districts, including bone." (PMID 32527062, 2020). "Our results suggest that the hypoxia-induced acidosis reduced BMAL1 independently of HIF-1α in breast cancer cells." (PMID 32316196, 2020). "HIF-1α is also well documented in breast cancer metastasis, as it controls the expression of EMT-related genes and matrix metalloproteinases essential to cell migration." (PMID 33266219, 2020). "In breast cancer cell lines, HIF-1α was found to increase the expression of adenosine receptor 2B (A2BR), which, as mentioned in earlier sections, plays a role in MDSC expansion and immunosuppression." (PMID 33256070, 2020). "Overexpression of MYC significantly stabilizes HIF1α and enhances HIF1α accumulation under both normoxic and hypoxic conditions in normal immortalized mammary epithelial cells and breast cancer cells." (PMID 33251216, 2020). "In breast cancer cells, HIF-1α stabilization induces the expression of the extracellular matrix remodeling enzymes lysyl oxidase and MMPs, leading to a more aggressive phenotype and metastasis." (PMID 33142239, 2020).
breast cancer (continued). "In breast cancer cell LCN2 can induce HIF1A expression, which is an important transcriptional factor mediated EDN1 gene expression in endothelial cells." (PMID 32968110, 2020). "In breast cancer, HIF-1α also controls the expression of cluster of differentiation 47 (CD47), an integrin membrane protein expressed on many different cell types for the regulation of a wide range of cellular processes." (PMID 33256070, 2020). "We first detected HIF-1α expression in CLDN6-overexpressing breast cancer cells and found that CLDN6 significantly decreased HIF-1α accumulation under hypoxia." (PMID 32093760, 2020). "We further demonstrated that SA inhibited breast cancer metastasis primarily by restraining late-stage autophagy via Hif-1α/Cav-1 signaling." (PMID 33381039, 2020). "Some natural compounds, such as diallyl trisulfides, reduce the expression of HIF-1α in breast cancer cell line (MDA-MB-231) inhibiting hypoxia-induced breast cancer metastasis." (PMID 32850424, 2020). "The positive signals of HIF-1α were diffusely distributed throughout the FMGC or restricted to perinecrotic neoplastic cells, consistent with the pattern of HIF-1α in human breast cancers." (PMID 32375802, 2020). "Our data put forward that in this luminal A breast cancer model GRK2 would foster HuR/HIF-1α pathways even in normoxic conditions." (PMID 32413989, 2020). "In particular, hypoxia-activated HIF-1α was found to cooperate with GPER in breast cancer cells and CAFs toward gene expression changes and relevant biological responses." (PMID 32778144, 2020). "Resveratrol (150 μM), suppressed uptake of glucose and glycolysis in T-47D breast cancer cells, associated with a reduction in GLUT1 expression and dependent on a reduction in intracellular ROS levels, which decreases HIF-1α accumulation." (PMID 31936350, 2020). "NRF2 promotes breast cancer progression by enhancing glycolysis through coactivation of HIF1α, which allows some to suggest NRF2 as a therapeutic target for breast cancer." (PMID 33371179, 2020). "In this study, the interaction between Hif-1α and Cav-1 was investigated during autophagy-mediated metastasis in breast cancer." (PMID 33381039, 2020). "However, the underlying mechanism of HIF‐1α in breast cancer stiffness remains unknown." (PMID 32436609, 2020). "In liver-metastasis prone breast cancer cells, HIF-1α triggers the glycolytic phenotype required for migration by directly expressing the enzyme pyruvate dehydrogenase kinase 1 (PDK1)." (PMID 33266219, 2020). "Nevertheless, both HSF4 and HSF2 have been indicated to modulate the expression of hypoxia-inducible factor 1-alpha (HIF-1α) in MCF-7 breast cancer cells." (PMID 32408596, 2020). "Subsequently, in breast cancer cells, HIF1α was reported to be crucial for upregulating circDENND4C under hypoxic conditions, indicating that circDENND4C is an HIF1α-associated circRNA and promotes the proliferation of breast cancer cells." (PMID 31973726, 2020). "Once Nur77 was depleted, the neutralizing effect of LNT on this signaling pathway was abrogated, indicating that LNT launched the degradation of HIF-1α was Nur77-dependent in breast cancer cells." (PMID 33245358, 2020). "Because of its important role in the PI3K/Akt/mTOR signaling pathway, mTOR and downstream HIF-1α have been experimentally suggested to be inhibited by miR-99a, which reverses the breast cancer stem cell malignant phenotype." (PMID 32014012, 2020). "Recent work showed that increased chemoresistance of breast cancer was mediated by HIF1α-mediated glutathione biosynthesis and glutathione-mediated enrichment with cancer stem cells." (PMID 32914752, 2020). "Taken together, these findings demonstrated that HIF‐1α and Kindlin‐2 are upregulated and interact with one another in breast cancer." (PMID 32436609, 2020).